FXYD5 (FXYD domain containing ion transport regulator 5)
Diseases named in the same sentence as FXYD5 in open-access papers (continued):
Sharing a sentence is not in itself a finding about the gene and the disease.
cancer (23 papers, 2011 to 2025). A tumor composed of atypical neoplastic, often pleomorphic cells that invade other tissues. "The enrichment of C0 FXYD5+ TCs in cancer tissues and their association with poor prognosis confirmed previous studies that FXYD5 expression is associated with increased epithelial-mesenchymal transition (EMT) and metastatic potential." (PMID 39717768, 2024). "Within the tumor cell population, seven distinct subtypes were recognized, with the C0 FXYD5+ tumor cells subtype being significantly linked to cancer progression and poor prognosis." (PMID 39717768, 2024). "Two family members, FXYD3 (mammary tumor protein 8 kD) and FXYD5 (dyshaderin or resembles ion channel), are highly expressed in numerous malignant tumors and are associated with tumor cell invasion and migration, involvement of lymph nodes and prognosis." (PMID 24396454, 2014). "FXYD5 encodes dysadherin, a cancer-associated glycoprotein that promotes tumour metastasis by downregulating E-cadherin in numerous human carcinomas." (PMID 21081927, 2011). "For example, up-regulation of FXYD5 has been shown to correlate with tumor size and poor survival in NSCLC and to be implicated in many cancer types as FXYD5 enhances NFκ-B transcriptional activity, promotes angiogenesis and increases tumor cell’s migration and invasion abilities." (PMID 38589970, 2024). "This pattern coincided with the upregulation of key markers associated with cancer stemness (CD133, CD44) and metastasis/invasion (MMP7, CD74), highlighting FXYD5 as a potential driver of malignant progression." (PMID 41457101, 2025). "Meanwhile, members of theFXYD protein family such as FXYD3 and FXYD5 play an important role in the pathogenesisof numerous malignant tumors and are used as indicators for the biologicalcharacteristics and prognostic factors of certain tumors." (PMID 33817214, 2020). "Altogether, these results lead us to propose FXYD5/Dys as a potential inflammation mediator in EC, facilitating monocyte recruitment to the tumor microenvironment and eventually promoting cancer progression, through NF-κB pathway activation." (PMID 31867269, 2019). "The roles of FXYD3 (Mat-8) and FXYD5 (dysadherin) are unclear, but they appear to be overexpressed in some cancer cells, and FXYD6 and 7 are expressed in the brain." (PMID 28634454, 2017). "In some cancer cell lines and tumors FXYD5 overexpression has been correlated with down-regulation of E-cadherin." (PMID 27066483, 2016). "FXYD3 and FXYD5 (dysadherin) are expressed in some normal tissues but are elevated in some types of cancer." (PMID 27014088, 2016). "In a number of clinical studies it was shown that there is a statistically significant correlation between the FXYD5 abundance and the progression of malignancies, accompanied by poor outcome of patients with various cancers." (PMID 27066483, 2016). "Despite the generally low PSI values for the 325 cryptic 3’SSs from the CLL-only analysis, we identified four genes previously implicated in cancer (TTI1, MAP3K7, FXYD5, PFDN5) and six others (YIF1A, ORAI2, ZNF91, ZNF548, RP11–1280I22." (PMID 25768983, 2015). "Thus, pulsing target cells with the inhibitor compounds induced the truncated cancer-associated O-glycan Tn29,63, which triggered ADCC activity by mAbs directed to Tn-glycopeptide epitopes in MUC1 and FXYD5." (PMID 36804936, 2023). "FXYD5 expression also appears to increase the metastatic potential of human cancers." (PMID 35371992, 2022). "Yet, the studies examining the role of FXYD5 in cancer cell behaviour are few." (PMID 34059618, 2021). "Hence, our results in OTSCC cells strengthens the previous findings for the tumour-promoting role of FXYD5 in other cancers." (PMID 34059618, 2021). "In addition, FXYD5/Dys expression was higher in Grade 3 tumors than in Grade 1 and Grade 2 tumors, as observed in other cancers." (PMID 31867269, 2019). "Some evidence has suggested the link of FXYD5 to known cancer promoting signaling pathways." (PMID 27066483, 2016).
cancer (continued). "For example, C0 FXYD5+ TCs are abundantly present in cancerous tissues, whereas C2 MUC2+ TCs and C4 OTOP2+ TCs are predominantly present in normal and para-cancer tissues." (PMID 39717768, 2024). "FXYD1, FXYD3, FXYD6 and FXYD7 were significantly downregulated in cancer samples, while FXYD4 and FXYD5 were markedly overexpressed." (PMID 34270462, 2021). "We found that orospheres overexpressed several genes, such as VEGF, FXYD5 (dysadherin), CXCR2, and MMP10, that have been strongly correlated with invasion and metastasis in many cancers, including H&N carcinomas." (PMID 25428916, 2015). "The use of FXYD5 expression as a prognostic factor has not been studied in other pathologies than cancer." (PMID 36119538, 2022). "In cancer cells, CCL2 has been identified as a mediator of FXYD5 effects on cell migration." (PMID 28620381, 2017).
tumor (23 papers, 2011 to 2026). "Analysis of The Cancer Genome Atlas Liver Hepatocellular Carcinoma (TCGA-LIHC, v32) dataset further confirmed elevated FXYD5 expression across tumor stages, and its association with reduced overall survival." (PMID 41457101, 2025). "Compared with those in control mice (ApcMin/+; Fxyd5+/+), the number of tumors and total tumor load in dysadherin KO (Fxyd5−/−) mice were significantly lower." (PMID 41535258, 2026). "In a diethylnitrosamine (DEN) / carbon tetrachloride (CCl4)-induced HCC mouse model, Fxyd5-knockout (KO) mice (Fxyd5−/−) developed fewer and smaller tumors, with significantly lower tumor incidence at 19 weeks, than wild-type controls did." (PMID 41457101, 2025). "Studies of stemness genes in various tumor subtypes have revealed that MYC is significantly expressed in C0 FXYD5+ TCs, suggesting that this subtype has a high proliferative potential and is critical for tumor growth." (PMID 39717768, 2024). "Enrichment analysis revealed that the C0 FXYD5+ tumor cell subtype exhibited increased energy metabolism, protein synthesis, and oxidative phosphorylation, contributing to its aggressive behavior." (PMID 39717768, 2024). "Tumoural FXYD5 expression is reported to inversely correlate with E-cadherin expression in many cancers, however we found only minimal decrease in the level of E-cadherin in MMP8 + HSC3 cells compared to control cells." (PMID 34059618, 2021). "Additional experiments are needed to further characterize the function of FXYD5 in vivo and the cleavage by neutrophil or tumour-derived MMP8 should be considered in experimental settings." (PMID 34059618, 2021). "Among Stage I tumors, higher FXYD5/Dys mRNA levels were found at the invasive front compared to the superficial section of the tumor (P = 0.0013)." (PMID 31867269, 2019). "In univariate survival analysis, OS and PFS were significantly shorter in patients with tumours exhibiting FXYD5 overexpression both at mRNA and protein level." (PMID 31434988, 2019). "In the present study, we detected a negative immunostaining signal in all normal controls and a significant FXYD5 protein overexpression in tumour samples from short-term survivors compared to long-term ones." (PMID 31434988, 2019). "Since FXYD5/Dys has been reported to promote cell motility in vitro in other tumor types, the impact of its knockdown in HGE cell migratory capacity was evaluated." (PMID 31867269, 2019). "During the past decade, a correlation between enhanced expression of FXYD5 and tumor progression has been established for various tumor types." (PMID 27066483, 2016). "Previous studies have reported that specific members of the FXYD protein family, including FXYD3 and FXYD5, play important roles in the pathogenesis of a number of tumor types." (PMID 24396454, 2014). "It has been reported that FXYD2, FXYD3 and FXYD5 are up-regulated in several types of tumors, leading to accelerated tumor growth and progression." (PMID 24715268, 2014). "Furthermore, immunofluorescence (IF) analysis revealed that compared with control (ApcMin/+) mice, dysadherin-KO (Fxyd5−/−) mice presented lower CA9 expression in primary tumor lesions." (PMID 41535258, 2026). "Furthermore, we analyzed the scRNA-seq dataset (GSE144735) and stratified tumor cells into dysadherin (FXYD5) high and low expression groups on the basis of median gene expression levels." (PMID 41535258, 2026). "Tumors with high expression of FXYD5+ TCs have higher immune cell infiltration and lower tumor purity, an observation that suggests that these tumors may be more resistant to immune checkpoint blockade therapy." (PMID 39717768, 2024). "Consistent with these in vitro data, fibronectin was significantly enriched on the membranes of dysadherin-expressing tumor cells within ApcMin/+;Fxyd5+/+ mouse intestinal tumors, and the enrichment of fibronectin was significantly decreased in dysadherin-deficient mouse tumors." (PMID 35673579, 2022).
tumor (continued). "FXYD5/Dys was highly expressed at the tumor invasive front compared to the superficial area." (PMID 31867269, 2019). "We proposed a relationship between FXYD5/Dys expression and EC tumor progression/aggressiveness." (PMID 31867269, 2019). "Moreover, the tumor invasive front had higher FXYD5/Dys mRNA levels than the superficial tumor section, suggesting an involvement of FXYD5/Dys in tumor dissemination." (PMID 31867269, 2019). "The results obtained after Hec1a EC cell modulation of FXYD5/Dys expression are in line with results obtained in EC patient samples showing higher FXYD5/Dys transcript levels in invasive EC (MI > 50%) and at the invasive tumor front, as well as in Grade 3 tumors." (PMID 31867269, 2019). "Altogether, these findings lead us to propose that an increased FXYD5/Dys expression could promote cell migration and dedifferentiation, in part through E-cadherin downregulation, in EC cells, thus facilitating MI and tumor dissemination." (PMID 31867269, 2019). "Altogether, these results lead us to propose an autocrine and/or paracrine regulation loop between FXYD5/Dys and the TGF-β1 pathway, in which TGF-β1 produced by the tumor microenvironment or by tumor cells could induce FXYD5/Dys expression in the tumor cell." (PMID 31867269, 2019). "Furthermore, we have found that overexpression of FXYD6 increases migration and proliferation in the human SMMC7721 cells, which agrees with the role of FXYD3 or FXYD5 overexpression in tumor progression." (PMID 24715268, 2014). "PD-L1 expression positively correlated with high expression levels of tumor promoting genes such as CD68, ADAM12, FXYD5, S100A11, CD46, and MED19 (and ST1D)." (PMID 33415077, 2020). "From the Human Tumor Metastasis RT-PCR array with ATAD2 siRNA-treated cells, we identified APC, ITGB3, FXYD5, ITGA7 and CTNNA1 (α-catenin), which are related to cell adhesion; among these, the expression of APC and CTNNA1 changed by at least 3-fold." (PMID 24552534, 2014). "On the other hand, tumor cells tended to show higher expression of LY6E, FXYD5, and TGFBI." (PMID 35974387, 2022). "Inspired by the close correlation between FXYD3/FXYD5 and tumor progression, we supposed that FXYD6 may be also involved in tumor malignancy." (PMID 24715268, 2014).
infection (1 paper, 2017). The state of being infected such as from the introduction of a foreign agent such as serum, vaccine, antigenic substance or organism. "The presence of the antibody decreased the cellular infiltration into the lung, stimulated by infection with Ad-FXYD5." (PMID 28620381, 2017). "In isolated primary mouse ATII, infection with lentivirus coding for specific shRNA FXYD5 prevented the LPS-stimulated increase in FXYD5 and CCL2 mRNA by 62 and 30%, respectively." (PMID 28620381, 2017). "To determine whether classical monocytes contribute to the FXYD5-induced inflammatory response, we infected mice with Ad-FXYD5 or Ad-Null, and 48 h after the infection depleted monocytes by the injection of an anti-CCR2 antibody." (PMID 28620381, 2017).
FXYD5 also shares sentences with these, for which no sentence is quoted: adenoma (2 papers); colorectal cancer (2); colon cancer (1); escherichia coli infection (1); glioma (1); Hypomagnesemia (1); lung carcinoma (1); Lung Injury (1); neuritis (1); schizophrenia (1); thyroid cancer (1).